SOCS3 (suppressor of cytokine signaling 3)
Diseases named in the same sentence as SOCS3 in open-access papers (continued):
Sharing a sentence is not in itself a finding about the gene and the disease.
melanoma (continued). "Over-expression of SOCS1 and SOCS3 proteins in melanoma cells was achieved using the PINCO retroviral vector, while siRNA were used to inhibit SOCS1 and SOCS3 expression." (PMID 20398276, 2010). "Twenty-four hours following transduction of human melanoma cell lines with the SOCS1 and SOCS3-expressing retroviral constructs or empty PINCO vector, the expression of EGFP was confirmed in each cell line by flow cytometry." (PMID 20398276, 2010). "Data from the present study have expanded our understanding of SOCS protein expression in melanoma and suggest that SOCS1 and SOCS3 proteins within the tumoral compartment represent a potential target that deserves investigation in future pre-clinical studies." (PMID 20398276, 2010). "Transduced melanoma cell lines over-expressed SOCS1 and SOCS3 proteins as determined by immunoblot analysis." (PMID 20398276, 2010). "In the present study we have demonstrated that human melanoma cell lines express basal levels of SOCS1 and SOCS3 and that these proteins are further increased upon stimulation with type I and type II IFNs." (PMID 20398276, 2010). "To test whether this inhibition impacts SOCS3 expression by microglia, we treated microglia cells with MCM of the four melanomas together with the three inhibitors." (PMID 37296634, 2023). "SOCS3 was also upregulated in microglia cells following treatment with unfractionated MBM or SF originating in all four melanoma cell lines but not by the EV fraction." (PMID 37296634, 2023). "We next set to identify melanoma-derived factors that may induce STAT3 phosphorylation and SOCS3 upregulation in microglia." (PMID 37296634, 2023). "Taken together, these results show that SOCS3 was involved in the progression of some but not all the four melanomas employed in this study." (PMID 37296634, 2023). "Furthermore, using the TIDE website, it was determined that patients with downregulated expression levels of SOCS3 had a higher overall survival rate after ICB (PD-1 or PD-L1) treatment among kidney cancer, melanoma, and bladder cancer patients." (PMID 35600392, 2022). "Another study on the 1286 melanoma cell line showed high SOCS-3 expression, the natural inhibitor of JAK/SAT3 signalling, and that forced suppression of SOCS-3 could render the cells again responsive to inhibitory effects of OSM or IL-6." (PMID 24381786, 2013). "No increase in SOCS1 or SOCS3 expression was observed in any melanoma cell line transduced with the empty PINCO vector." (PMID 20398276, 2010). "To determine whether the overexpression of the SOCS proteins can directly affect melanoma invasion and/or suppress the effect of IFNβ, we prepared stable cell lines bearing EGFP-tagged doxycycline-inducible SOCS1 and SOCS3 (iSOCS1 and iSOCS3) gene expression constructs." (PMID 32872349, 2020). "SOCS1 and SOCS3 expression and anti-tumor function have been also elucidated in skin cancer contexts, such as non-melanoma skin cancer (NMSC) and melanoma." (PMID 38975347, 2024). "Although the effect of SOCS1 or other SOCS family members (i.e. SOCS3) on IFN-α-responsiveness of melanoma cells was not evaluated in this prior study, our observations suggest that SOCS1 and SOCS3 could be a clinically relevant inhibitor of cytokine action." (PMID 20398276, 2010).
prostate carcinoma (32 papers, 2010 to 2025). A carcinoma that arises from epithelial cells of the prostate gland. "SOCS3 methylation decreased mRNA level and significantly associated with a more aggressive behavior and worse prognosis in prostate cancer." (PMID 28404963, 2017). "In harmony with this assumption, SOCS-3 expression has been shown to increase during development and progression of prostate cancer and enhances glioblastoma cell survival, its loss converting the anti-apoptotic function of STAT-3 into pro-apoptotic." (PMID 24593195, 2014). "The locus for Socs3, also implicated in prostate cancer, is just 2 megabases away from the integration site." (PMID 23308238, 2013). "There are reports associating either increased or reduced expression of SOCS3 with breast and prostate cancer." (PMID 23028842, 2012). "Many retrospective studies underlined that an elevated SOCS3 expression significantly correlated with DFS and OS in patients with BC, colorectal cancer, gastric cancer, ovarian cancer, and prostatic cancer." (PMID 40003884, 2025). "In prostate cancer, EGR3 suppresses metastasis by inducing the expression of tumor suppressor genes, such as ZFP36 and SOCS3, while additional evidence suggests that EGR3 loss correlates with relapse and reduced survival." (PMID 40649712, 2025). "That study demonstrated its ability to activate specific genes—ZFP36, GADD45B, and SOCS3—in a prostate cancer cell line." (PMID 38543002, 2024). "In other types of cancer such as pancreatic cancer, prostate cancer, or glioblastoma, SOCS3 promotes tumor progression as its upregulation leads to tumor cell proliferation, migration and angiogenesis." (PMID 37296634, 2023). "SOCS3 overexpression in castration-resistant prostate cancer cells increases the sensitivity to the killing by natural killer cells." (PMID 35818076, 2022). "Although there are reports ofeither increased or decreased SOCS3 expression in breast and prostate cancer, SOCS3functions as a tumor suppressor in most cancer types including gastric cancer, HCC, andcolon cancer." (PMID 34450627, 2021). "The crosstalk between IFN and androgen signaling appears to be bidirectional given that IFN can induce Dtx3L/Parp9, and AR can repress IFN signaling through induction of genes such as SOCS3 in prostate cancer cells." (PMID 33976187, 2021). "SOCS3 hypermethylation was linked to constitutive activation of STAT3 and unfavorable clinical outcomes in prostate cancer and to enhanced epithelial cell proliferation in gastric cancer." (PMID 34439155, 2021). "The studies about MDSCs in prostate cancer demonstrated that SOCS3 negatively regulated the development and function of MDSCs by inhibiting STAT3 activation." (PMID 30083161, 2018). "Prostate cancer patients who have methylation in the promoter region of SOCS3 presented a more aggressive phenotype." (PMID 28077171, 2017). "SOCS3 gene has been reported to be hypermethylated in various types of cancers, including endometrial carcinoma, prostate cancer, Barrett esophagus carcinoma, and ulcerative colitis-related colorectal cancer." (PMID 28404963, 2017). "SOCS3 hypermethylation was also seen in glioma and also in prostatic cancer where aberrant methylation of SOCS3 was found in 39% of cases of prostate cancer in contrast to all benign (BPH) cases and normal control which showed a SOCS3 promoter nonmethylation." (PMID 24757565, 2014). "Previously we demonstrated that Ad-SOCS3 could inhibit the growth of human and mouse prostate cancer cells via inhibition of interleukin-6 (IL-6)/JAK/STAT signaling." (PMID 37064130, 2023). "Additionally, lncRNA LINC00893 regulated the suppressor of SOCS3/JAK2/STAT3 pathway by acting as a ceRNA to bind with miR-3173-5p in patient with prostate cancer." (PMID 37620751, 2023). "Additionally, we observed also observed down regulation SOCS3 with reduced transcripts of Bcl-2 in prostate cancers cells with regards to apoptosis." (PMID 29278364, 2017).
prostate carcinoma (continued). "SOCS3 is upregulated in prostate cancer and inhibits the induction of apoptosis by cAMP." (PMID 20553623, 2010). "Inhibition of suppressor of cytokine signaling 3 (SOCS3) expression by miR-2909 upregulates Stat1 and its downstream target Isg15 in prostate cancer cells." (PMID 36319753, 2022). "MiR-221 directly inhibited SOCS3 expression and enhanced IFN-γ sensitivity in prostate cancer cells." (PMID 34439155, 2021). "Regarding MDSCs, recent studies demonstrated that SOCS3 negatively regulates the development and function of MDSCs via inhibition of STAT3 activation in prostate cancer." (PMID 29326716, 2017). "SOCS3 interferes with the FGF-2 signalling pathway by modulating p44 and p42 phosphorylation in prostate cancer cells." (PMID 24757565, 2014). "Other data show that there is an inverse correlation between the expression of SOCS-3 and IL-6-induced phosphorylation of STAT3 in prostate cancer cells; furthermore, downregulation of SOCS-3 by a short interfering RNA approach resulted in inhibition of proliferation and an increased apoptotic rate." (PMID 29234375, 2017). "Particularly, SOCS1 and SOCS3 have been postulated as candidates to regulate the radio and chemoresistance acquisition in other types of cancer, such as prostate cancer, or cervix cancer, but there is a lack of studies regarding the role of SOCS1 and SOCS3 in radiotherapy resistance in GBM." (PMID 30811476, 2019).
atherosclerosis (31 papers, 2012 to 2025). A disease characterized by the build-up of fatty material and calcium deposition in the arterial wall resulting in partial or complete occlusion of the arterial lumen. "It has been observed that loss of SOCS3 can induce an anti-inflammatory MØ phenotype, which is beneficial in limiting vascular inflammation and atherosclerosis progression." (PMID 40607379, 2025). "In atherosclerosis, platelets induce SOCS3 expression in macrophages, causing them to differentiate into inflammatory phenotypes and secrete inflammatory cytokines, thereby promoting plaque formation." (PMID 38867262, 2024). "V55 increased expression of Socs3 and Dab2 genes (inhibitors of cytokine signaling and NF-κB pathway), Apoe (associated to atherosclerosis control), Igf1 (encoder a protein with analogous effects to insulin) and Fgf10 (fibroblasts growth factor)." (PMID 35631379, 2022). "In another study, milk-derived tripeptides decrease proinflammatory cytokines IL-1β, IL-6 as well as SOCS3 in the abdominal aorta of ApoE-deficient mice, thus reducing atherosclerosis development." (PMID 33801489, 2021). "It suggests that ruxolitinib may attenuate atherosclerosis by inhibiting JAK2/STAT3/SOCS3 signaling pathway, while the detailed underlying mechanisms still need further studies." (PMID 32169038, 2020). "Moreover, (3S)-vestitol up-regulated the expression of Socs3 and Dab2 genes (inhibitors of cytokine signaling and the NF-κB pathway), Apoe (related to atherosclerosis control), Igf1 (encoder a protein with analogous effects to insulin) and Fgf10 (fibroblasts growth factor)." (PMID 35631379, 2022). "In the model of atherosclerotic rabbits, the phosphorylation levels of JAK2 and STAT3 were increased, and the expression of SOCS3 was also upregulated, indicating that inhibition of JAK2/STAT3/SOCS3 signaling can alleviate atherosclerosis." (PMID 37089432, 2023). "In this study, we designed experiments to further investigate the effect of JAK2/STAT3/SOCS3 signaling in rabbit atherosclerosis process." (PMID 32169038, 2020). "SOCS3 is a potent inhibitor of pro-inflammatory pathways involved in atherosclerosis and the development of NIH." (PMID 29367551, 2017). "Accordingly, the over-expression of SOCS3 in T cells reduced IL-17 levels and accelerated atherosclerosis and severe aortic aneurysm formation." (PMID 24600449, 2014). "The over-expression of SOCS3 in T cells reduced IL-17 and accelerated atherosclerosis whereas the in vivo treatment with anti-sense oligodeoxynucleotides targeting SOCS3 exacerbated the atherosclerotic process in ApoE−/− mice." (PMID 24600449, 2014). "What's more, it was demonstrated that PLT can accelerate atherosclerosis formation by regulating the expression levels of cytokines like SOCS3 and IL-1β, inducing monocyte macrophages to produce inflammatory features, and promoting monocyte recruitment at plaques." (PMID 40980181, 2025). "A literature review revealed that flavanones could inhibit the IL6/JAK/STAT3/SOCS3 signaling pathway and improve atherosclerosis." (PMID 35799780, 2022). "The raised inflammatory milieu driven by VSMCPCSK9-EVs was confirmed by the protein expression of phosphorylated form of STAT3 (signal transducer and activator of transcription 3) and SOCS3 (suppressor of cytokine signaling-3), two well-known cell signalling pathways involved in atherosclerosis." (PMID 36361853, 2022). "The observed anti-inflammatory and antioxidant properties of KIRCONG chim corroborate the potential application of SOCS3 mimetics in inflammatory diseases, including atherosclerosis, even if its low aqueous solubility and high molecular weights hamper their direct use as drugs." (PMID 35047557, 2021). "Taken together, our findings suggest that the inhibition of JAK2/STAT3/SOCS3 signaling may attenuate atherosclerosis in rabbits." (PMID 32169038, 2020).
atherosclerosis (continued). "SOCS3, whose expression level increased continuously along with the elongation of feeding in ApoE−/− mouse aortas, is closely correlated with atherosclerosis progression because it plays a regulatory role in the expression and activation of IL-6, TNF-α, as well as other inflammatory cytokines." (PMID 32169038, 2020). "Furthermore, we found that JAK2 and STAT3 phosphorylation were up-regulated in rabbits with atherosclerosis when compared with those of the control group, followed by the expression of SOCS3 was also increased due to the activation of JAK2 and STAT3." (PMID 32169038, 2020). "Moreover, miR-19b in endothelial cell-derived microvesicles promotes atherosclerosis progression by increasing PVAT-specific inflammation by diminishing SOCS3 (suppressor of cytokine signaling 3) expression." (PMID 33391033, 2020). "From those results, we finally concluded that the inhibition of JAK2/STAT3/SOCS3 signaling may attenuate atherosclerosis in rabbits." (PMID 32169038, 2020). "Considering the important role of JAK2/STAT3/SOCS3 signaling pathway played in the inflammatory process in atherosclerosis, the potentially therapeutic strategy may be expected for the treatment of patients with atherosclerosis." (PMID 32169038, 2020). "Taken together, the inhibition of JAK2/STAT3/SOCS3 signaling pathway may be a novel method for the clinical treatment of artery atherosclerosis." (PMID 32169038, 2020). "SOCS1 was atheroprotective in mouse models while the absence of macrophage SOCS3 of apoE(−/−) mice attenuates disease, confirming a causal link between macrophage SOCS3 and atherosclerosis." (PMID 25120543, 2014). "Novel treatments based on the regulation of SOCS3 protein levels could therefore have value in the treatment of diseases with an inflammatory component, such as atherosclerosis." (PMID 23782265, 2013). "Clearly novel treatments based on the regulation of SOCS3 levels in cells could have value in the treatment of diseases such as atherosclerosis where there is hyperactivation of JAK/STAT3 signalling." (PMID 23782265, 2013). "Thus, EPAC1 is involved in multiple anti-inflammatory processes in VECs and the links between EPAC1 and SOCS3 and the development of atherosclerosis/NIH indicate that EPAC1 regulation should be considered as a potential therapeutic avenue for the future treatment of cardiovascular disease." (PMID 29367551, 2017). "The accumulation of SMC_C1 (SOCS3+ ACTA2+) in the group of OCA and EC_C1 (DARC+ CD31+) in the group of atherosclerosis was further validated using pathological staining." (PMID 37706320, 2023). "A central component of this is the ability of SOCS3 to limit IL-6 signalling and thus protect against NIH and CABG restenosis, and other inflammatory diseases such as atherosclerosis." (PMID 30719343, 2019). "In contrast, overexpression of SOCS3 suppresses JAK/STAT signalling and the development of atherosclerosis and NIH, demonstrating the importance of SOCS3 in limiting the development of cardiovascular disease." (PMID 29367551, 2017). "By contrast, either overexpression of SOCS3 or introduction of SOCS-derived peptides has been shown to suppress JAK–STAT signalling, acute inflammation, and the development of atherosclerosis and NH, illustrating the important protective role of SOCS3." (PMID 25744542, 2015). "SOCS3 has previously been studied in both DTH and atherosclerosis." (PMID 36172348, 2022). "In atherosclerosis, antisense suppression of SOCS3 in APOE -/- mice exacerbated atheroma development, whereas adenovirus-mediated upregulation of SOCS3 in the same model suppressed plaque development, in association with reduction in STAT1 and STAT3-dependent gene expression." (PMID 36172348, 2022). "The gene SOCS3, suppressor of cytokine signalling 3, plays a pivotal role in the innate immune system as a regulator of cytokine signalling along the JAK/STAT pathway and was previously reported to have an important role in the processes of atherosclerosis." (PMID 31205673, 2019).
atherosclerosis (continued). "Thus, the combination of previous and current research results revealed that TNF, CXCL8, SOCS3 and TNFAIP3 may be involved in chronic inflammatory lesions that eventually result in atherosclerosis, CAD or IS." (PMID 32164735, 2020). "However, whether ruxolitinib plays a key role in atherosclerosis process and JAK2/STAT3/SOCS3 signaling pathway is still not well understood." (PMID 32169038, 2020).